CRP (C-reactive protein)
Diseases named in the same sentence as CRP in open-access papers (continued):
Sharing a sentence is not in itself a finding about the gene and the disease.
periodontitis (continued). "Epidemiological data show that in patients with periodontitis, serum levels of inflammatory biomarkers such as C-reactive protein (CRP) are increased compared to those without periodontitis." (PMID 37759326, 2023). "They concluded that neither the amount of the reduced nor the elevated baseline CRP levels were related to the severity of periodontitis." (PMID 38077410, 2023). "Our study demonstrated that 5% of the GG genotype was found in the moderate–severe periodontitis group, while none of the GG genotype was found in the mild periodontitis group based on the CRP -757 A/G gene." (PMID 37239434, 2023). "This study found a positive correlation between CRP and CAL, the serum CRP levels significantly positive correlated with the CP severity increasing in dialysis patients, indicating that periodontitis was probably an important source of systemic inflammation in PD patients." (PMID 36964507, 2023). "Periodontitis is characterized by a nonspecific acute‐phase response with acute‐phase reactants like CRP." (PMID 37070360, 2023). "This trend was also apparent for IL-6 (participants with severe periodontitis = 1.77; participants with none/mild periodontitis = 1.45) and CRP (severe = 0.13; none/mild = 0.10)." (PMID 36056348, 2022). "Minimally invasive periodontal surgery with EMD in periodontitis-affected subjects results in lower values of C-reactive protein as no inflammatory perturbation was noticed." (PMID 35563469, 2022). "Salivary fetuin-A levels were significantly lower in patients with chronic periodontitis than healthy individuals, and a negative correlation between fetuin-A and CRP levels was observed." (PMID 35966877, 2022). "The aim of this study is to compare hs-CRP levels of self-reported periodontitis cases versus cases without periodontitis in PD patients." (PMID 35418117, 2022). "Compared to periodontally healthy patients, non-treated periodontitis (stage 2–4) subjects showed significantly lower levels of lymphocytes upon admission and higher levels of D-dimer, CRP and ferritin before discharge." (PMID 35906340, 2022). "(a) shows a mean difference of 1.20mg/l in CRP with a p value<0.00001 (95% CI: 1.13 ~ 1.27, heterogeneity I2 =0%, P=0.58), suggesting that NSPT significantly reduced the serum CRP level in CAD patients with periodontitis." (PMID 36243997, 2022). "In both studies, saliva samples were collected during the 3rd trimester and authors found a higher prevalence of periodontitis as well as significantly higher levels of TNF-α, IL-1β, total antioxidant capacity (s-TAC) and CRP, particularly when GDM was diagnosed." (PMID 36432584, 2022). "Thanakun and Izumi demonstrated a significant elevation of plasma CRP, but a reduction of adiponectin, in patients with severe periodontitis (SP), irrespective of body mass index (BMI)." (PMID 33603787, 2021). "NSPT reduces serum levels of leptin and CRP and enhances serum levels of adiponectin in Thai patients with Owt/Ob, irrespective of periodontitis severity." (PMID 33603787, 2021). "Patients with Owt or Ob had higher plasma levels of CRP and leptin, but lower levels of adiponectin, compared with normal weight (Nwt) participants, irrespective of periodontitis status." (PMID 33603787, 2021). "Strikingly, all the included patients presented periodontitis and periodontitis-specific blood markers (antibodies against the periodontal pathogens Pg and Aa and also LPS and CRP) although periodontitis was not an inclusion criterion of the study." (PMID 35096635, 2021). "NSPT reduces serum levels of CRP and leptin while enhancing serum levels of adiponectin, in Thai patients with Owt or Ob, irrespective of periodontitis severity." (PMID 33603787, 2021). "A study on the effects of non-surgical periodontal treatment on serum CRP levels found that systemic inflammation in patients with CKD resulted from periodontitis." (PMID 34211440, 2021).
periodontitis (continued). "Some authors reported significantly higher CRP levels in the gingival crevicular fluid of individuals with periodontitis, as compared to healthy controls, but not in the gingivitis group." (PMID 34439905, 2021). "A lack of difference regarding the CRP levels has also been reported by other studies, while the more sensitive serum amyloid A has been shown to be detected in higher levels in periodontitis patients compared to healthy controls." (PMID 34408814, 2021). "Patients with periodontitis exhibited consistently higher values of CRP compared to healthy controls irrespective of the laboratory assessment adopted." (PMID 34394107, 2021). "Serum reactive oxygen species, interleukin (IL)-1, IL-6, tumor necrosis factor (TNF)-α, and CRP have been found to be elevated in the bloodstream of patients with established T2DM and may play an important role in tissue breakdown in periodontitis." (PMID 33924022, 2021). "Observational and intervention studies that: 1) evaluated CRP and hs-CRP serum levels in patients with and without periodontitis, and; 2) hs- CRP levels after NSPT were included." (PMID 34394107, 2021). "The results of the present study showed that individuals with periodontitis presented a significantly higher level of CRP in comparison with individuals without periodontitis." (PMID 32994872, 2020). "In the final logistic regression model, individuals with periodontitis were more likely to present altered C-reactive protein than individuals without periodontitis (OR=3.27, CI=1.42-7.52, p=0.005)." (PMID 32994872, 2020). "In fact, compared to subjects with a healthy periodontium, patients with periodontitis have higher values of circulating white blood cells (WBC) and/or of systemic inflammatory parameters such as C-reactive protein (CRP), a protein produced by the liver as a response to an external insult." (PMID 32486269, 2020). "In this study, individuals with periodontitis presented higher levels of CRP in comparison with individuals without periodontitis." (PMID 32994872, 2020). "Moreover, the association between both saliva and serum MAA levels in patients with periodontitis and with CHD was assessed, and if the salivary or serum MAA levels are mediated by serum CRP." (PMID 31805680, 2019). "In contrast to these findings, in 154 patients on HD, the mean serum CRP level in those with severe periodontitis was reported to be similar to that in those without periodontitis (9.27 and 11.90 mg/dL, respectively; p = 0.28)." (PMID 31382656, 2019). "Indeed, the acute-phase reactants, interleukin (IL)-6, C-reactive protein (CRP), haptoglobin, fibrinogen, serum amyloid A, and serum amyloid P are elevated in periodontitis patients." (PMID 31293577, 2019). "In periodontitis, there is an increase in the production of proinflammatory mediators, such as IL-1β, TNF-α, IL-6, IFN-γ, and the levels of acute-phase proteins, such as CRP." (PMID 35919481, 2019). "Stimulating oxidative stress conditions, such as periodontitis and CVD, may have led to the high production of CRP levels, which in turn could stimulate serum and salivary MAA to protect cells from tissue damage due to oxidative stress." (PMID 31805680, 2019). "In this study, we did not observe any association between periodontitis severity and RA disease activity in terms of DAS28, the self-assessed health (HAQ-score) or in the levels of CRP (serum, saliva or GCF)." (PMID 31072030, 2019). "On this platform we found only a slight stepwise increase in CRP with the severity of periodontitis but not significant." (PMID 29439734, 2018). "Several studies have stated that patients with severe periodontitis had statistically significant elevated serum CRP compared to those without periodontitis." (PMID 30477167, 2018). "In addition to CRP, it has been reported that SAA proteins are also elevated in patients with chronic periodontitis." (PMID 28326084, 2017).
periodontitis (continued). "We determined the levels of IgG to three major periodontal pathogens, A. actinomycetemcomitans, P. gingivalis, and P. intermedia, and CRP in patients with MS with and without periodontitis." (PMID 26871443, 2016). "Increased levels of α-1-AGP and CRP during arthritis in rats have previously been reported, however, to our knowledge this is the first study reporting the levels of α-1-AGP in co-morbid rats with also experimental periodontitis." (PMID 27809921, 2016). "Anne et al17 and Radafshar et al15 evaluated the effect of non-surgical treatment of periodontitis on the serum levels of these proteins in severe periodontitis group and reported that periodontal intervention diminished the serum levels of CRP." (PMID 27651883, 2016). "In summary, we identify higher levels of CRP, eotaxin and MCP-1 in serum of periodontitis patients." (PMID 26241961, 2015). "In contrast, serum levels of KC (mouse homolog of IL-8) and CRP were not significantly different between mice with experimentally induced periodontitis and controls." (PMID 25806806, 2015). "Patients with aggressive periodontitis have statistically significant elevations in serum CRP levels compared to subjects without periodontitis." (PMID 26346216, 2015). "Interestingly, we show increased CRP and MCP-1 levels in normal weight patients, thus suggesting that both BMI and periodontitis can contribute to a systemic increase in these markers." (PMID 26241961, 2015). "Since data on clinical periodontal status and inflammatory markers such as CRP were not available in this study, a potential interaction between clinical periodontitis and systemic antibody responses cannot be determined." (PMID 25522313, 2014). "The level of serum high-sensitivity CRP (hs-CRP), an acute-phase reactant that has been reported to predict the outcome of CVD, was found to be more increasing in patients with periodontitis than in control subjects, and it decreased significantly after periodontal treatment." (PMID 24526921, 2014). "Periodontitis increases systemic inflammatory burden leading to worsening of CKD which in turn has been has been found to negatively affect CKD of patients on hemodialysis therapy by altering their serum albumin and C-reactive protein levels." (PMID 24353542, 2013). "The aim of this trial is to compare the effect of two periodontal treatment approaches on levels of C-reactive protein, lipids, flow-mediated dilation and serum concentrations of proinflammatory and endothelial markers in stable CAD patients with periodontitis over a period of 12 months." (PMID 24010954, 2013). "CRP levels in RA patients with severe periodontitis were higher than in RA patients without periodontitis (marginally significant, P = 0.05)." (PMID 23075462, 2012). "Given that most of the current studies examining the association between selected variables (such as blood lipids and CRP) and periodontitis are observational non-cohort studies, these mediating effects require support from longitudinal studies and mechanism studies." (PMID 40672423, 2025). "However, no significant changes in the leukocyte counts and CRP levels were observed probably due to the chronic nature of periodontitis in the present cases because CRP is more elevated in acute inflammation." (PMID 40552326, 2025). "The pathogenesis of periodontitis involves a dysbiotic oral microbiota triggering a sustained host immune response, leading to elevated systemic levels of pro-inflammatory cytokines such as tumor necrosis factor-alpha (TNF-α), interleukin-6 (IL-6), and C-reactive protein (CRP)." (PMID 41030757, 2025). "Several pro-inflammatory and bone-regulatory molecules, such as interleukin (IL)-1β, IL-6, IL-8, IL-17, C-reactive protein (CRP), matrix metalloproteinases (MMPs), and receptor activator of nuclear factor kappa-Β ligand (RANKL), have been extensively investigated as biomarkers in periodontitis." (PMID 41356214, 2025).
periodontitis (continued). "However, no statistically significant reduction of CRP was observed in periodontitis patients without any comorbidities (otherwise healthy)." (PMID 38877442, 2024). "We believe that the abundant expression of CRP and MIP-1α in resident inflammatory conditions such as AMI and periodontitis could be due to aggravated periodontal breakdown, resulting in the expression of antimicrobial peptides due to a dysbiotic environment in the microbial dental film." (PMID 38433948, 2024). "Although it cannot be concluded that periodontitis in the ESRD patients was a major contributing factor to their increased level of serum CRP, their inflammatory periodontal status may lead to increased levels of CRP." (PMID 39396133, 2024). "Generally, it is challenging to evaluate systemic CRP levels in non-smokers and smokers because both smoking and periodontitis may stimulate increased CPR levels." (PMID 38627806, 2024). "In exposed individuals, serum CRP levels increased progressively from healthy periodontium to gingivitis, stable periodontitis, and unstable periodontitis and were significantly higher than in non-exposed participants, reflecting elevated CRP levels in women across these conditions." (PMID 37038173, 2023). "The CRP-717 T/C gene is not related to periodontitis including in the Indonesian population." (PMID 37239434, 2023). "Patients with levels of CRP below 0.6 mg/dL could be in the quiescence period of periodontitis, which gives a negative finding for in terms of CRP levels." (PMID 37568846, 2023). "Therefore, CRP also exhibits different responses to PG in perimenopausal women with periodontitis in the presence or absence of SRP." (PMID 37645411, 2023). "The patients with CRP levels below 0.6 mg/dL could be in the quiescence period of periodontitis, which may have resulted in negative findings for the CRP levels." (PMID 37568846, 2023). "Our findings provide evidence that a higher pre-pregnancy BMI may lead to increases in CRP levels during pregnancy in women with periodontitis, irrespective of the severity of clinical periodontal parameters." (PMID 35270396, 2022). "The exploratory hypothesis was that pre-pregnancy BMI would be independently associated with changes during pregnancy and early postpartum in inflammatory markers (CRP, IL-6, and MMP-9) and anti-inflammatory cytokine (IL-10) concentrations in pregnant women with periodontitis." (PMID 35270396, 2022). "Periodontitis may act as a non-traditional cardiovascular risk (CVR) factor, linked by a low-grade systemic inflammation mediated by C-reactive protein (CRP)." (PMID 34439905, 2021). "However, SRP together with 7-day antibiotic therapy (amoxicillin + metronidazole, 500 mg each, 3 times daily) does not change salivary levels of GSH or C-reactive protein (CRP) in patients with periodontitis." (PMID 33353105, 2020). "C-reactive protein and alkaline phosphatase are considered two nonspecific inflammatory markers, which rise in peripheral blood circulation and gingival crevicular fluid as a sign of active periodontitis." (PMID 33344675, 2020). "This fact may explain why some individuals without periodontitis presented significant changes in CRP levels." (PMID 32994872, 2020). "In rats: a ligature-induced (Lig) periodontitis model and Aβ25-35-induced model of Alzheimer’s disease (AD) were established; tumor necrosis factor-α (TNF-α), interleukin 1 (IL-1), interleukin 6 (IL-6), and C-reactive protein levels in the hippocampus and cerebral cortex were detected." (PMID 32614834, 2020). "As a support of the present study, several lines of evidence have shown that stimulating oxidative stress conditions, such as periodontitis and CAD, may have led to the lower the production of vitamin C, which in turn could augment serum and salivary CRP levels." (PMID 31817129, 2019).
periodontitis (continued). "Furthermore, systemic levels of inflammatory mediators, including C-reactive protein (CRP), TNF-α, and IL-6, which are elevated in periodontal diseases, may represent the linchpin between DM and periodontitis." (PMID 30897827, 2019). "In a subset of patients with severe periodontitis, locally produced proinflammatory mediators—such as IL-1β, IL-6, and TNF-α—can enter systemic circulation and induce an acute-phase response in the liver that is characterized by an increased level of C-reactive protein (CRP)." (PMID 28243243, 2017). "In the most recent meta-analysis of the effects of periodontal treatment on CRP levels, Teeuw and coworkers analyzed and presented separately the results from subjects with periodontitis, but otherwise healthy (without co-morbidities) and those from subjects with co-morbidities." (PMID 28190975, 2017). "In another study of 5,552 participants, it was found that the mean CRP level was approximately one-third higher in subjects that clinically presented with periodontitis than compared to subjects with little or no signs of periodontitis." (PMID 28326084, 2017). "We analyzed a spectrum of cytokines and chemokines in serum from individuals with and without periodontitis and could through multivariate PLS modeling identify eotaxin and MCP-1, CRP, years of smoking and age as periodontitis associated factors." (PMID 26241961, 2015). "According to our data, there is a salivary CRP concentration difference between the healthy subjects and patients with gingivitis, also the difference in concentration between patients with gingivitis and periodontitis was not significant." (PMID 24551806, 2013). "Although their cause and effect relationship has not been established, but it is likely that elevation of CRP levels in periodontitis may help to understand the relationship between cardiovascular diseases and periodontitis." (PMID 24551806, 2013). "Thus, it is not surprising that high levels of CRP have been observed in peripheral blood samples in patients with type 1 diabetes and severe periodontitis." (PMID 22322513, 2012). "Some studies reported by these authors establish that patients suffering from severe Periodontitis have an increased local production of inflammatory cytokines (IL-1B, TNF-α and IL-6) and a moderate systemic inflammatory response characterized by raised concentrations of CRP, and other mediators." (PMID 28348657, 2011). "Besides, systemic inflammatory biomarkers such as C-reactive protein (CRP) and IL-6 may not fully reflected the local periodontal inflammation, resulting in the inability of DII to sensitive feedback the risk of periodontitis." (PMID 40612309, 2025). "Finally, this study could address the interactive roles between periodontitis and CRP at a baseline point because the NHANES was not a panel study and did not include time-varying information on periodontitis and CRP statuses." (PMID 39453923, 2024). "Thus, it implies that periodontal infection may contribute to systemic inflammation and a course of non-surgical treatment of moderate periodontitis did influence circulating serum levels of CRP." (PMID 38077410, 2023). "However, there was no statistical difference of the marker’s levels in periodontitis patients with and without chronic hepatitis C. After NSPT the GCF CRP levels decreased in HCV+P patients but showed a contradicting slight increase in periodontitis-only patients." (PMID 34830557, 2021). "Although CRP is a non-specific biomarker, the present findings suggest that periodontitis may contribute to the elevated CRP concentrations and support the relationship between periodontitis, inflammation, and AAA instability." (PMID 35096635, 2021). "As highlighted by the ELISA analysis of the PTX3 and CRP markers in gingival fluid samples, it could be said that non-surgical periodontal therapy has a relevant, improving, impact on the local homeostasis of periodontitis + hepatitis C patients." (PMID 34830557, 2021).